IGF2BP1 (insulin like growth factor 2 mRNA binding protein 1)
Diseases named in the same sentence as IGF2BP1 in open-access papers (continued):
Sharing a sentence is not in itself a finding about the gene and the disease.
cancer (continued). "In addition, targeting IGF2BP1 and IGF2BP3 could be more specific for tumors and safer for patients, given their absence in normal tissues and high levels in many cancers." (PMID 37280679, 2023). "Insulin-like growth factor 2 mRNA-binding proteins (IGF2BPs; IGF2BP1/2/3), as a newly discovered m6A regulator in recent years, promotes the stability and storage of its target mRNA (such as MYC) in an m6A-dependent manner, and has a carcinogenic effect in cancer." (PMID 34206803, 2021). "Collectively, these data support the notion that IGF2 might not be the major mediator of IGF2BP1-modulated oncogenic effects in cancer." (PMID 33673232, 2021). "Likewise, BTYNB decreased E2F1 expression and vitality of all other here investigated cancer cell lines without affecting IGF2BP1 abundance." (PMID 32761127, 2020). "Note worthily, a small molecule, BTYNB, might function as a potential therapeutics by inhibiting cell proliferation of IGF2BP1-positive cancer cells without effect in IGF2BP1-negative cells." (PMID 29954406, 2018). "The insulin-like growth factor-2 mRNA-binding protein 1 (IGF2BP1), a member of a conserved family of single-stranded RNA-binding proteins (IGF2BP1-3), expresses in a broad range of fetal tissues and more than 16 cancers but only in a limited number of normal adult tissues." (PMID 29954406, 2018). "Furthermore, 3′UTR shortening-mediated upregulation of IGF2BP1/IMP-1 could lead to cellular phenotypes such as oncogenic transformation, demonstrating the importance of APA regulation in cancer." (PMID 29031844, 2017). "Therefore, we focused our attention on two related RNA binding proteins, IGF2BP1 and IGF2BP3, which bind and control CD44 mRNA stability in several cellular system and their expression is tightly related to CD44 levels in several forms of cancer." (PMID 26429859, 2015). "BTYNB may restrain binding of IGF2BP1 to the coding region stability determinant of c-Myc mRNA and downregulate several mRNA transcripts including c-Myc, β-TrCP1, and eEF2 both in IGROV-1 and SK-MEL2 cancer cells, as well as decrease activation of nuclear transcriptional factors-kappa B (NF-κB)." (PMID 29954406, 2018). "For instance, circXPO1 is upregulated in lung adenocarcinoma and interacts with IGF2BP1 without influencing its expression to promote its function of stabilizing CTNNB1, leading to cancer progression." (PMID 37554271, 2023). "A significant positive correlation was detected between IGF2BP1 expression and MSI in cancers such as KICH, LUSC, MESO, OV, and SARC; while, a significant negative correlation between IGF2BP1 expression and MSI was observed in COAD." (PMID 36686749, 2022). "In view of lacking correlation of IGF2BP1 and MYC mRNAs across cancers, this provided further evidence that IGF2BP1-dependent regulation of MYC mRNA levels is rather cell-type specific." (PMID 32761127, 2020). "This might be due to the fact that IGF2BP1 and IGF2BP3 are oncofetal proteins that are not expressed in most adult tissues but often reactivated in cancer, whereas IGF2BP2 expression is retained throughout adulthood." (PMID 37503349, 2023). "However, the role of IGF2BP1 and its paralogs in regulating Type I and II IFN signaling affecting innate and adaptive immune responses in cancer cells and outcomes of immunotherapies were not previously reported." (PMID 37503349, 2023). "For example, IGF2BP1 and IGF2BP2 have a shared consensus GG(m6A)C binding sequence, though in adult cancer cells, the binding of IGF2BP1 and not IGF2BP2 results in the protection of some oncogenic transcripts (e.g., SRF) from miRNA-directed transcript downregulation." (PMID 32707690, 2020).
adenocarcinoma (7 papers, 2015 to 2024). A common cancer characterized by the presence of malignant glandular cells. "Interestingly, this study underlined some genes, such as IGF2BP1, as a possible common driver of adenocarcinomas, and Liver X receptor activation, as a pathway upregulated in adenocarcinomas and downregulated in squamous cancers." (PMID 28930282, 2017). "We therefore developed an HTS assay to look for small molecules that would inhibit Igf2bp1 binding to Kras RNA, in order to identify molecules that could have therapeutic benefit in preventing Igf2bp1-mediated adenocarcinomas." (PMID 34895045, 2022). "Conversely, IGF2BP1 and IGFBP2 expressions significantly correlated with IGF-1 and IGF-2 expressions and adenocarcinoma incidence (p < 0.05)." (PMID 31480481, 2019). "Interestingly, the IGF2BP1, IGF2BP2, and HNRNPC genes displayed strong prognostic performance in adenocarcinoma, as validated in two independent cohorts of patients." (PMID 38539567, 2024). "Two patients (one stage II and one stage IV adenocarcinoma patients without receiving any treatment) had low IGF2BP1 H-scores compared to paired adjacent normal tissues." (PMID 34203267, 2021).
infection (7 papers, 2016 to 2025). The state of being infected such as from the introduction of a foreign agent such as serum, vaccine, antigenic substance or organism. "Compared to mock-infected (Caco-2)/uninfected (HBECs) cells, IGF2BP1 levels started to increase in both cell lines and reached almost four-fold higher levels (log2 fold change = 1.89) 48 h after infection in the HBECs." (PMID 37515119, 2023). "In the DHAV-1 infected ducklings, the increased viral protein expression derived by IGF2BP1 would stimulate the immune system to produce higher levels of neutralizing antibodies to resist DHAV-1 infection." (PMID 31658691, 2019). "SGs containing IGF2BP1 protein induced by MuV infection (24 h post-infection) were only reduced by ~50% in TIA-1- or G3BP1-KD cells compared with control cells, although mRNA expression was decreased to a greater extent (data not shown)." (PMID 27560627, 2016). "Moreover, IGF2BP1 expression levels reached a moderate yet significant elevation after 8 days of infection in these cells." (PMID 37515119, 2023). "In addition, they found that the knockdown as well as knockout of IGF2BP1 in different cell lines led to reduced levels of viral RNA in these cells after infection with SARS-CoV-2." (PMID 37515119, 2023). "Thus, due to a basal expression of IGF2BP1 in healthy human kidneys, they could potentially be organs vulnerable for infection by SARS-CoV-2 that might be intensified by IGF2BP1." (PMID 37515119, 2023). "Remarkably, however, upon infection with HBV, HCV, SARS-CoV-2, DHV-1 and ARV, increasing levels of IGF2BP1 RNA and/or protein have been observed." (PMID 37515119, 2023). "Besides the putative influence on the natural infection process, an inhibitory effect of IGF2BP1 on HIV-1 production, facilitated by binding to Gag and Rev proteins, might also impact research and gene therapy approaches using lentiviral vectors comprising HIV-derived genes." (PMID 37515119, 2023). "We also confirmed that IGF2BP1 knockout (KO) significantly repressed both SARS-CoV-2 (MOI 0.05) and ZIKV (MOI 0.5) infections in IGF2BP1-KO Huh7 cells." (PMID 34737357, 2022). "Nonetheless, IGF2BP1 RNA levels tended to increase over time in infected cells, whereas the levels of SARS-CoV-2 genomic RNA started to decrease in Caco-2 cells between 12 and 24 h after infection, while they continued to increase in HBECs until the final measurements (96 h)." (PMID 37515119, 2023). "To determine the impact of these modifications on IGF2BP1 function, we transduced CD34+ cells from four healthy adult donors with the parental SIiP virus or versions that included the 2A-puromcyin (SI2AP) or 2A-ZsGreen (SI2AZG) cassette at equivalent multiplicities of infection (MOIs)." (PMID 32154328, 2020).
hematological malignancies (2 papers, 2021 to 2024). "Although many specific IGF2BP1 small molecule inhibitors have been recently identified in solid cancers, few were applied to hematological malignancies." (PMID 39342091, 2024). "Finally, we discussed the limitations of IGF2BP1 as a potential therapeutic target for hematological diseases." (PMID 39342091, 2024). "In this paper, we systematically summarized the studies on IGF2BP1 in recent years and elucidated the mechanism of IGF2BP1 in regulating embryogenesis, hematologic malignancies, and hematologic genetic diseases, providing some clues for the diseases that target IGF2BP1." (PMID 39342091, 2024). "Additionally, several studies have highlighted the importance of IGF2BP1 in hematologic malignancies and hematological genetic diseases, positioning it as a promising therapeutic target for hematological disorders." (PMID 39342091, 2024). "From the analysis on the “Total” data set IGF2BP1, ALKBH5, IGF2BP2, RBM15, METTL3, ZNF217 is the potentially carcinogenic gene in hematological malignancies." (PMID 33816257, 2021).
inflammation (1 paper, 2023). Aberrant reaction of the microcirculation characterized by movement of fluid and leukocytes from the blood into extravascular tissues. "The regulating function of IGF2BP1 in E2F1 and MIF expression during acute renal inflammation in vivo was then examined." (PMID 36632449, 2023).
neurodegenerative disease (1 paper, 2025). A disorder of the central nervous system characterized by gradual and progressive loss of neural tissue and neurologic function. "In our present study, four m6A feature regulators (YTHDC1, IGFBP1, IGF2BP1, and ALKBH5), critically implicated in psychiatric disorders and neurodegenerative diseases, were identified to be associated with PTSD." (PMID 41149057, 2025).
IGF2BP1 also shares sentences with these, for which no sentence is quoted: lung squamous cell carcinoma (3 papers); Crohn disease (2); cutaneous melanoma (2); diabetic angiopathy (2); intrahepatic cholangiocarcinoma (2); ischemic stroke (2); paraganglioma (2); pheochromocytoma (2); squamous cell carcinoma (2); testicular cancer (2); adrenocortical carcinoma (1); Alzheimer disease (1); bladder urothelial carcinoma (1); cardiovascular diseases (1); chronic myeloid leukemia (1); connective tissue disorder (1); COVID-19 (1); diabetic retinopathy (1); gallbladder carcinoma (1); gastrointestinal carcinomas (1); head and neck cancer (1); hematologic tumors (1); hepatoblastoma (1); Hypoglycemia (1); infertile (1); iron deficiency (1); Klinefelter syndrome (1); mastitis (1); metastatic melanoma (1); microphthalmia (1).
A further 17 diseases each share a sentence with IGF2BP1 in 1 paper.